ATP7A (ATPase copper transporting alpha)
Diseases named in the same sentence as ATP7A in open-access papers (continued):
Sharing a sentence is not in itself a finding about the gene and the disease.
Menkes disease (continued). "Menkes disease (MD), a representative of copper metabolism disorders, is an X‐linked lethal neurodegenerative condition caused by mutations in the ATP7A gene, which encodes a copper‐transporting P1B‐type ATPase." (PMID 39267265, 2024). "Menkes disease (MD) is a rare X-linked genetic disorder with multisystem involvement due to copper transport defects caused by mutations in the ATP7A gene." (PMID 38926644, 2024). "Failure in the cuprostatic network results in a variety of pathologies—including Menkes disease (MD), occipital horn syndrome, and Wilson's disease (WD), caused by mutations in the Cu+-P-type ATPases ATP7A and ATP7B." (PMID 39375833, 2024). "Mutations in the ATP7A gene cause Menkes disease (MD), occipital horn syndrome (OHS), and distal motor neuropathy (DMN)." (PMID 38674035, 2024). "Dysregulation of copper metabolism leads to various diseases, exemplified by Menkes disease (MD) and Wilson’s disease (WD) which are caused by loss-of-function mutations in the copper transporter ATP7A or ATP7B, respectively." (PMID 39290994, 2024). "Deficiency in ATP7A could cause Menkes disease, characterized by copper defect." (PMID 36474131, 2023). "Thus, the novel ATP7A mutation associated with Menkes disease expands the ATP7A gene spectrum." (PMID 36936426, 2023). "However, it is not known whether orally supplied ES can escort copper through polarized enterocytes to be effective in treating the severe systemic copper deficiency found in animal models of Menkes disease or under conditions of complete Atp7a ablation." (PMID 35433682, 2022). "In humans, a lack of ATP7A activity caused by mutations in the X-linked ATP7A gene leads to Menkes disease (MD), a rare and lethal genetic disorder of the copper metabolism." (PMID 36232742, 2022). "Moreover, premature death from congenital defects of Cu transporters (ATP7A) in Menkes disease and progressive neurodegeneration due to CP deficiency cause fatal neurological consequences, this study provides further evidence for the importance and impact of Cu-dependent proteins on neuron survival." (PMID 36430330, 2022). "Disease-causing variants in ATP7A lead to two different phenotypes associated with copper deficiency; a lethal form called Menkes disease (MD), leading to early death, and a much milder form called occipital horn syndrome (OHS)." (PMID 33967692, 2021). "It is worth mentioning that the other study that uses a similar method for two X-linked diseases (Menkes disease and ATP7A-related disorders) also found a very low number of variants, which could suggest that this strategy is not the best approach for X-linked disorders." (PMID 33208168, 2020). "For example, Menkes disease (MD), which has several alleles in the ATP7A gene that are associated with alternative splicing defects, is a lethal disorder of copper metabolism that lead to severe neurological degeneration." (PMID 28443131, 2017). "Mutations in ATP7A give rise to copper deficiency disorders, of which Menkes disease (MD) is best described." (PMID 26861285, 2016). "Menkes disease (MD) is a copper metabolism disorder that is caused by a loss-of-function of a major copper transporter, ATP7A." (PMID 26347346, 2015). "Mutations in ATP7A are associated with Menkes disease (MD), while ATP7B mutations cause Wilson's disease (WD)." (PMID 24904274, 2014). "Menkes disease (MD) is an X-linked recessive disorder caused by mutations in the gene ATP7A, which encodes a copper-transporting P-type ATPase." (PMID 22815746, 2012). "Menkes Disease (MD) is a rare X-linked recessive fatal neurodegenerative disorder caused by mutations in the ATP7A gene, and most patients are males." (PMID 22264391, 2012). "Menkes disease (MD) is an X-linked, fatal neurodegenerative disorder of copper metabolism, caused by mutations in the ATP7A gene." (PMID 22074552, 2011).
Menkes disease (continued). "This work uncovered a genetically link between the Snca and Atp7a gene functions, major proteins of Parkinson’s disease and Menkes disease, respectively, via a modifier screen." (PMID 40678754, 2025). "The importance of ATP7A in Cu delivery is evident from the Menkes disease phenotype, where inactivation of ATP7A results in brain Cu deficit, neurodegeneration, and death in early childhood." (PMID 39172219, 2025). "In the present study, we identified a novel insertion in exon 3 of ATP7A in a patient with Menkes disease." (PMID 41393994, 2025). "While heterozygous deletion of exons 16 and 17 of the ATP7A gene was detected in the proband, her mother, and her grandmother, only the proband suffered from Menkes disease clinically." (PMID 38172222, 2024). "While heterozygous exon skipping of ATP7A was observed in the proband, her mother, and her grandmother, only the proband manifested clinical features of Menkes disease." (PMID 38172222, 2024). "ATP7A is primarily studied in related disorders such as Menkes disease and occipital horn syndrome, and its role in copper transport is well-documented." (PMID 39337685, 2024). "While heterozygous deletion of the ATP7A gene was inherited from her grandmother to her mother and the proband, only the proband suffered from Menkes disease clinically." (PMID 38172222, 2024). "MEDNIK syndrome is caused by a pathogenic variant in the AP-1 sigma (σ) subunit, and shares multiple symptoms and cellular phenotypes with Wilson and Menkes disease, hence indicating the possible involvement of AP-1 in regulation of ATP7A and ATP7B." (PMID 38032054, 2024). "Menkes disease phenotypes have been reported in females with X chromosome; autosome translocations—disrupting ATP7A gene function—or ATP7A gene alterations." (PMID 38248841, 2024). "We diagnosed a female infant with Menkes disease and identified heterozygous deletion of exons 16 and 17 of ATP7A, with a familial skewing of XCI." (PMID 38172222, 2024). "Two homologous Cu transporters, Atp7a (Menkes disease protein) and Atp7b (Wilson disease protein), maintain Cu homeostasis in the tissue." (PMID 36626371, 2023). "ATP7A, also known as Menkes disease protein, is a P-type ATPase that transports Cu2+ across cell membranes." (PMID 37259030, 2023). "More recently, in Menkes disease and ATP7A-related symptoms, copper histidine or copper chloride injections were effective in improving developmental and neurological issues in patients." (PMID 37458582, 2023). "Menkes disease, occipital horn syndrome (OHS), and ATP7A-related distal motor neuropathy are disorders caused by the alteration in ATP7A, an X-linked gene encoding a Cu-binding ATPase." (PMID 36677007, 2023). "Mutations in the genes encoding ATP7A and ATP7B cause inherited disorders of Cu metabolism, known as Menkes’ disease and Wilson’s disease, respectively." (PMID 38139406, 2023). "For example, overexpression of the protein ATP7A with an AAV2/5 vector (AAV2/5-rsATP7A) mitigates the Menkes disease phenotype involving copper metabolism in the Atp7a knockout mouse model." (PMID 35619113, 2022). "Mosaic mutant mice displaying a functional dysfunction of ATP7A are an established model of Menkes disease." (PMID 36232742, 2022). "Yeast, fruit flies, zebrafish, and mice have all been used as model organisms to understand the role of ATP7A in copper metabolism and evaluate potential treatments for Menkes disease." (PMID 35433682, 2022). "We here summarize the current knowledge of the roles of copper enzyme function in Menkes disease, with a focus on ATP7A-mediated enzyme metalation in the secretory pathway." (PMID 33917579, 2021). "Genetic alteration in Cu-regulating ATPases, ATP7A, and ATP7B can cause Menkes disease (MD) and Wilson disease (WD), respectively." (PMID 34577062, 2021). "The copper pump, ATP7A is critical for whole-body, cellular, and subcellular copper homeostasis, and dysfunction due to genetic defects results in Menkes disease." (PMID 33917579, 2021).
Menkes disease (continued). "A better therapeutic response is obtained in newborns with Menkes’ disease, showing albeit residual ATP7A activity, who were more likely to respond to this treatment than newborns with complete loss-of-function mutations." (PMID 33291628, 2020). "Particularly mutations in the human homologues crp genes ATP7A and ATP7B cause X-linked Menkes disease and autosomal recessive Wilson’s disease, respectively." (PMID 32862758, 2020). "More recently, the addition of the ATP7A gene targeting the brain in a Menkes disease mouse model has shown promising results." (PMID 33291628, 2020). "Menkes disease (OMIM 309400) is a copper deficiency disorder inherited in an X-linked recessive fashion and mutations in the ATP7A gene (OMIM 300011) have been associated with this disorder." (PMID 31835360, 2019). "Mutations in ATP7A cause copper deficiency, which can lead to the development of several disorders such as Menkes disease, occipital horn syndrome, and ATP7A-related distal motor neuropathy." (PMID 31213024, 2019). "Mutations in genes encoding ATP7A and ATP7B cause two genetic disorders of Cu homeostasis, Menkes disease and Wilson disease, respectively." (PMID 31540259, 2019). "In mice with the Menkes disease (Atp7a mutants) phenotype, also significantly less NETs were detected in the course of endotoxemia." (PMID 32010131, 2019). "In the case of ATP7A related disorders (Menkes disease or occipital horn syndrome), the uptake of intestinal copper is deficient, leading to low serum copper, low ceruloplasmin but also low copper in liver tissue." (PMID 29321044, 2018). "Menkes disease is dominated by early childhood neurodegeneration whose mechanisms remain poorly understood, thus making ATP7A an ideal candidate to identify metal homeostasis mechanisms capable of modulating neuropathology phenotypes." (PMID 28355134, 2017). "Recently two missense mutations in copper transporters ATP7B (Wilson disease gene) and ATP7A (Menkes disease gene) that were respectively positively and negatively associated to hepatic copper levels were identified in Labrador retrievers." (PMID 28459846, 2017). "In comparison, the estimated frequency of deletions in the ATP7A gene (Menkes disease) in almost the same cohort (2500) of patients is 17%." (PMID 27992490, 2016). "Deficiency of one of the copper transporters ATP7A and ATP7B leads to the rare X-linked disorder Menkes Disease (MD) or the rare autosomal disorder Wilson disease (WD), respectively." (PMID 27587995, 2016). "Menkes disease (MD) is caused by mutation in the ATP7A gene." (PMID 27629586, 2016). "Mouse Atp7a mutants closely mimicking patients with Menkes disease serve as animal models of this inherited disorder and have recently been extensively used to explore metabolic copper-iron interactions." (PMID 25247420, 2014). "Menkes disease (OMIM: 309400) is an X-linked recessive neurodegenerative disorder, resulting from a mutation in the gene coding for the copper transporting ATPase (ATP7A)." (PMID 25506448, 2014). "These two novel findings obtained using the zebrafish atp7a model suggest new therapeutic strategies that focus on tissue-specific gene replacement for treating patients with Menkes syndrome." (PMID 24639652, 2014). "This explains why dysfunction of ATP7A protein in Atp7a mutants results in toxic copper accumulation at the renal-proximal epithelium, a phenomenon detected in various mouse models of Menkes disease, including mosaic mice." (PMID 25247420, 2014). "Cellular export of copper is mediated by the copper ATPases ATP7A and ATP7B which are mutated in the human disorders Menkes disease and Wilson's disease, respectively." (PMID 23503037, 2013). "ATP7A is a 178 kDa, Cu(I)-transporting P1B-type ATPase, and defects in ATP7A are responsible for Menkes disease." (PMID 23738776, 2013). "In dietary copper absorption, for example, the Golgi-resident Menkes gene ATP7A is critical and patients with Menkes disease exhibit severe bodily copper shortage." (PMID 24063361, 2013).
Menkes disease (continued). "In Menkes disease patients with some residual and functional ATP7A, less neurological pathology is observed." (PMID 23055972, 2012). "Menkes Disease (MD [MIM 309400]) is a rare X-linked recessive disorder, with an incidence of about 1:298.000 and is caused by mutations in the gene ATP7A [MIM 300011]." (PMID 22264391, 2012). "Menkes disease (MD) (OMIM #309400) is an X-linked recessive disorder of copper metabolism; it is caused by mutations in the ATP7A gene." (PMID 22992316, 2012). "The consequences of copper deficiency in humans are illustrated by Menkes disease (OMIM 390400), a pediatric disorder of copper metabolism caused by mutations in the ATP7A gene (NM_000052)." (PMID 22900086, 2012). "Menkes disease (MD; MIM# 309400) is a multisystemic lethal disorder of impaired copper metabolism due to mutations in the X-linked ATP7A gene." (PMID 22074552, 2011). "When screening the coding region of the ATP7A gene in patients with Menkes disease or Occipital Horn Syndrome, we identified a total of 33 novel splice site mutations." (PMID 21494555, 2011). "Me32a cells were derived from a Menkes disease patient and have a deletion in the ATP7A gene that introduces a premature stop codon." (PMID 21188142, 2010). "The copper transporter Atp7a is also affected in Menkes disease in humans, which has skeletal defects among its symptoms." (PMID 18419805, 2008). "The markedly improved survival of the mouse model of Menkes disease treated with ES-Cu demonstrated a major role of mitochondria in Menkes disease pathogenesis as well as a relatively higher importance of ATP7A activity in brain barriers compared to brain cells." (PMID 39172219, 2025). "Menkes disease patients, who lack the functional Cu transporter ATP7A and have impaired Cu delivery to the brain, show hypomyelination, abnormal vasculature, catecholamine misbalance, defects in axonal arborization and synaptogenesis, neuronal degeneration, and other pathologies (see Refs." (PMID 39172219, 2025). "A recent finding that the endogenous metabolite a-lipoic acid can decrease Cu toxicity in cultured Atp7a-/- cells by improving cellular redox environment raises a question whether a-lipoic acid can be used to improve kidney function in Menkes disease patients." (PMID 39172219, 2025). "Menkes disease is the most clinically severe disease on an allelic spectrum of ATP7A-related disorders, which includes occipital horn syndrome (OHS; MIM 304150), and X-linked distal spinal muscular atrophy type 3 (SMAX3; MIM 300489)." (PMID 38141875, 2024). "Severe vascular phenotypes are more common in Menkes disease but, infrequently, arterial disturbances are also observed in occipital horn syndrome which could be explained by the level of disruption to ATP7A activity." (PMID 37001705, 2023). "Menkes Disease (MD, MIM # 309400) is an X-linked recessive disorder of copper metabolism caused by pathogenic variants in ATP7A (OMIM # 300011) with an incidence of 1 in 300,000 in Europe, but it results less frequently in Japan and more frequent in Australia probably due to a founder effect." (PMID 35200700, 2022). "Moreover, elesclomol alleviates defects observed in murine model of Menkes disease in which function of ATP7A, a homologue of yeast Ccc2, is impaired." (PMID 33668157, 2021). "The lack of functional ATP7A is associated with severe connective tissue defects in Menkes disease patients, likely due to disrupted delivery of Cu to lysyl oxidase in the secretory pathway." (PMID 33407701, 2021). "This hypothesis was definitively tested with an enterocyte-specific knock-out of the murine Atp7a gene that fully recapitulates Menkes disease." (PMID 32422592, 2020). "An example is Menkes disease which is caused by the absence of or defecst in two Cu-transporting ATPases encoded by the ATP7A gene, which affects the absorption of Cu ions in the gastrointestinal tract." (PMID 32806787, 2020).
Menkes disease (continued). "The mutation in the ATP7A gene does not necessarily lead to Menkes disease; it has also been described in patients suffering from hereditary motor neuropathy which results in the weakness of the upper limbs that progresses with age." (PMID 32806787, 2020). "However, there have been five reports of Menkes disease affecting female patients with translocations that damaged ATP7A." (PMID 32344861, 2020). "An important role of ATP7A is well illustrated by the phenotype of Menkes disease (OMIM #30940)." (PMID 33291628, 2020). "Presently, we know that genetic defects affecting the copper-transporter P-ATPase, ATP7A, cause three X-linked recessive rare diseases: occipital horn syndrome (OMIM 304150), spinal muscular atrophy, distal, X-linked 3 (SMAX3, OMIM 300489), and Menkes disease (OMIM 309400)." (PMID 32422592, 2020). "Possibly the altered TAp73-dependent regulation of ATP7A during ageing could produce neuro-toxic effects responsible for progressive neurodegeneration similar to the severe manifestations observed in Menkes Disease." (PMID 30530920, 2018). "Moreover, only one of these conditions has a gene defect located on the X-chromosome (Menkes disease, ATP7A)." (PMID 28170433, 2017). "Then, we briefly highlight key P-type ATPases involved in neuronal disorders such as the copper transporters ATP7A (Menkes disease), ATP7B (Wilson disease), the Na+/K+-ATPases ATP1A2 (familial hemiplegic migraine) and ATP1A3 (rapid-onset dystonia parkinsonism)." (PMID 24904274, 2014). "Menkes disease (MD, OMIM #309400) is a fatal multisystem disorder of copper metabolism, primarily caused by intragenic variants or partial deletions in the ATP7A gene (OMIM #300011)." (PMID 41393994, 2025). "Similarly, PKDYS2 is often confused with Menkes disease due to the presence of the ATP7A gene." (PMID 40291937, 2025). "Similar to ATP7B, ATP7A is also involved in the copper death process, and the related diseases it affects have three manifestations: Menkes disease (MNK), occipital horn syndrome (OHS) and X‐linked distal spinal muscular atrophy 3 (SMAX3)." (PMID 39936900, 2025). "Dysregulation of copper metabolism is disadvantageous for cells because mutations in ATP7A and ATP7B are directly responsible for Menkes disease (MD) and Wilson disease (WD), respectively." (PMID 37767404, 2023). "Consistent with their important roles in maintaining health, mutations in ATP7A and ATP7B cause inherited disorders of Cu metabolism, which have been recognized as Menkes disease (MD) and Wilson’s disease (WD), respectively." (PMID 36414625, 2022). "Being allelic with Menkes disease (MD, OMIM#30011), OHS is considered the milder end of the phenotypic spectrum due to pathogenic variants in ATP7A that encodes a copper transporter." (PMID 31336972, 2019). "Loss-of-function mutations in copper transporters, such as ATP7A and ATP7B, lead to hereditary diseases, Menkes disease (MD), or WD." (PMID 28197076, 2017). "Studies of another animal model of Menkes disease, macular mice, found Cu accumulation within the BBB components, i.e., astrocytes and endothelial cells in agreement with the important role of ATP7A-mediated efflux of Cu from the cells of BBB." (PMID 39172219, 2025). "Excess copper is removed from the cell by the ATP-driven copper transporters ATP7A and ATP7B, protecting cells from ROS, and defects can lead to copper storage diseases like Menkes disease." (PMID 38263136, 2024). "Menkes disease (MNK; MIM 309400) is an X-linked syndrome caused by mutations in ATP7A." (PMID 34572285, 2021). "Analysis of Cu-transport by this and other mutants was monitored in Menkes disease fibroblast (YST) cells, which lack active ATP7A and ATP7B." (PMID 32778786, 2020). "Menkes disease (MD; OMIM: 309400), including the milder form Occipital Horn Syndrome (OHS; OMIM: 304150), is a rare (1:300.000), X-linked, multisystemic lethal disorder of copper metabolism linked to mutations in the ATP7A gene (OMIM: 300011)." (PMID 28389643, 2017).